ABCA4 (ATP binding cassette subfamily A member 4)
Diseases named in the same sentence as ABCA4 in open-access papers (continued):
Sharing a sentence is not in itself a finding about the gene and the disease.
Retinal dystrophy (continued). "Few studies have been conducted on ABCA4-associated retinal dystrophies in Taiwan." (PMID 33261146, 2020). "In the present study, we found that ABCA4-associated retinal dystrophies are a common disease-causing gene in Taiwan, and their phenotypes could be variable, mainly presenting as STGD1 and arRP, but also some cases of CRD." (PMID 33261146, 2020). "The extensiveness of retinal involvement might be regarded as a spectrum of ABCA4-associated retinal dystrophies." (PMID 33261146, 2020). "CRD and RP were believed to be more severe phenotypes of ABCA4-associated retinal dystrophies." (PMID 33261146, 2020). "In addition to CEP290, several other of the most frequently mutated inherited retinal dystrophy genes, e.g., ABCA4, EYS, and USH2A have a cDNA size way exceeding this limit and hence are not amenable for AAV-based gene therapy." (PMID 26325627, 2015). "The identification of compound heterozygous variants, including a novel likely pathogenic variant, suggests the phenotypic spectrum of ABCA4 may be broader than currently recognized, underscoring the necessity of comprehensive genetic analysis in atypical retinal dystrophies." (PMID 41458191, 2026). "The inconclusive cases in our cohort included patients with monoallelic pathogenic ABCA4 variants (5/18), monoallelic or biallelic VUS in ABCA4 (7/18), or VUS in other retinal dystrophy genes (6/18)." (PMID 41234456, 2025). "The variant with the highest frequency was c.5603A>T in the ABCA4 gene, with a heterozygous/homozygous frequency of 0.04042 in GnomAD and 0.039314516 in GME, and was associated with a complex retinal dystrophy phenotype on ClinVar." (PMID 41465088, 2025). "A genotype-phenotype correlation model elucidated that residual activity of the ABCA4 protein was correlated with the severity of retinal dystrophy." (PMID 40606666, 2025). "The parafoveal hyperpigmented ring observed in Proband A resembles bull's-eye maculopathy (BEM), often seen in inherited retinal dystrophies such as those caused by POC1B, ABCA4, CRX, and GUCY2D mutations." (PMID 41293231, 2025). "Pathogenic variants in ABCA4 have now been recognized as a major global cause of IRDs, accounting for 30% of all autosomal recessive IRDs1 and giving rise to a broad spectrum of phenotypes termed ABCA4-retinal dystrophies (ABCA4-RDs)." (PMID 39087934, 2024). "The study showed that the WDR19-Stargardt phenotype is within the phenotypic spectrum of ABCA4-Strgardt disease, stressing the importance of genetic testing in patients with inherited retinal dystrophies." (PMID 36833218, 2023). "Further, three genes, ABCA4, MYO7A and NR2E3, are shown to have an association to PRC thickness and have a prior association with retinal dystrophies." (PMID 36848389, 2023). "Along with RPE65-mediated IRDs, other monogenic retinal dystrophies have been the focus of gene therapy studies, particularly for ABCA4 and RS1-related IMDs." (PMID 37298674, 2023). "ABCA4 is nevertheless included in the EYE-RISK genotype assay for AMD, as retinal dystrophies are an important differential diagnosis in patients presenting with macular pathology." (PMID 35923205, 2022). "In a study including 16 patients with ABCA4-related retinal dystrophies, most of the patients (9/16) also revealed reduced IRAF, whereas for the other patients (4/16), a few small hyperAF dots in IRAF corresponding to hyperAF dots in BAF were observed." (PMID 31574917, 2019). "The present pilot study was designed to evaluate central retinal function following oral supplementation of a Crocus sativus extract S, in patients suffering from ABCA4-related STG/FF retinal dystrophy." (PMID 31618812, 2019). "In fact, alterations in near-infrared-autofluorescence, which is a marker for melanin, were identified as the earliest detectable retinal change in patients with ABCA4-related retinal dystrophies and can be used for predicting the further disease progress." (PMID 30038866, 2018).
Retinal dystrophy (continued). "We identified four phenotypic subgroups similar to 1) mitochondrial retinopathy, 2) adult vitelliform or pattern dystrophy, 3) fundus dystrophy similar to LORD or Sorsby fundus dystrophy or 4) PRPH2- or ABCA4-related retinopathy." (PMID 29555955, 2018). "Of these patients, seven had monoallelic pathogenic variants in ABCA4, one had biallelic variants of uncertain significance (VUS) in ABCA4, two had monoallelic VUS in ABCA4, and eight harbored VUS in other retinal dystrophy-related genes, including KCNV2, RIMS1, CRB1, CFH, RP1L1, UNC119, and SEMA4A." (PMID 41234456, 2025). "Biallelic pathogenic variants in the NCBI Gene: ABCA4 gene cause autosomal recessive inherited Stargardt disease (STGD1), as well as other forms of inherited retinal dystrophies (i.e., cone and cone-rod dystrophy, fundus flavimaculatus, and retinitis pigmentosa)." (PMID 38274366, 2024). "We have previously detected 10 missense variants of unknown significance (VUS) in patients with suspected ABCA4-retinal dystrophies (ABCA4-RDs) in Norway." (PMID 39087934, 2024). "Second, we recruited only patients who underwent long-term observations, mostly the proband of each family, rather than all patients with identified ABCA4-associated retinal dystrophies." (PMID 33261146, 2020). "Variants in the ABCA4 gene are responsible for STGD1, retinitis pigmentosa (RP), cone–rod dystrophy (CRD), and retinal dystrophy." (PMID 31543898, 2019). "A total of 101 additional individuals were sequenced in this study, 86 of them were relatives of positive ABCA4Rs (29 affected relatives, 51 carriers and 6 healthy), while 15 of them were negative for ABCA4, but all of them had mutations in other genes related to hereditary retinal dystrophies." (PMID 39162841, 2024). "An added complication lies in the comparable presentations of Stargardt’s and AMD, albeit usually in younger and older patients, respectively, with consensus favouring the role of ABCA4 as limited to Stargardt’s and related retinal dystrophies and mimicking, rather than causing AMD." (PMID 35923205, 2022). "Additionally, the prevalence of patients affected by retinal dystrophy carrying an ABCA4 mutation with another causative gene for their retinal dystrophy is not rare." (PMID 28061825, 2017). "ABCA4 gene mutations have been found to be responsible for five autosomal recessive retinal dystrophy phenotypes, including CORD3, RP19, FFM, STGD1, and early-onset severe retinal dystrophy." (PMID 29437900, 2018). "Except for ABCA4 mutations in 19 of 33 probands, potential mutations have not been detected in the other 14 probands after analysis of other 213 genes in which mutations were responsible for different forms of retinal dystrophy based on comprehensive whole exome analysis." (PMID 26161775, 2015). "Interestingly, genes involved in microphthalmia (VAX1, ALDH1A3, GJA1, and SMOC1) and retinal dystrophies (ADAMTS9, KCNJ13, CA2 and ABCA4) were also selected." (PMID 37479765, 2023). "These mutations were all present in ABCA4, but not in the other four STGD-associated genes or in genes responsible for other retinal dystrophies." (PMID 26161775, 2015).
retinitis pigmentosa (53 papers, 2005 to 2026). Retinitis pigmentosa (RP) is an inherited retinal dystrophy leading to progressive loss of the photoreceptors and retinal pigment epithelium and resulting in blindness usually after several decades. "This case of retinitis pigmentosa with atypical macular sparing highlights the diagnostic challenges in ABCA4‐retinopathy." (PMID 41458191, 2026). "Retinitis pigmentosa was the most represented phenotype (56%), followed by cone dystrophy (11%) and Leber congenital amaurosis (7%), while ABCA4 was the most frequently mutated gene (18%), followed by USH2A (9%) and RPGR (5%)." (PMID 35836572, 2022). "ABCA4-related retinitis pigmentosa in patients is frequently caused by combinations of ABCA4 null mutations such as frameshift and splicing site mutations." (PMID 33732702, 2021). "This study describes a patient with retinitis pigmentosa caused by a mutation in the ABCA4 gene with complex allele c.1622T>C, p.L541P; c.3113C>T, p.A1038V in homozygous state." (PMID 26229699, 2015). "They described one case showing severe retinitis pigmentosa, which presented a homozygous splice mutation (c.1938-1 G>A) at the ABCA4 locus, due to maternal deletion." (PMID 17277736, 2007). "Complete loss of ABCA4 causes severe photoreceptor degeneration (retinitis pigmentosa) in human." (PMID 26343735, 2015). "Specifically, we detected pathogenic DNA variants (∼50% novel mutations) in the genes RP1, USH2A, CNGB3, NMNAT1, CHM, and ABCA4, responsible for retinitis pigmentosa, Usher syndrome, achromatopsia, Leber congenital amaurosis, choroideremia, or recessive Stargardt/cone-rod dystrophy cases." (PMID 23940504, 2013). "ABCA4 is one of the most prevalent IRD-causing genes across populations, with its variants accounting for 2%–5% of non-syndromic retinitis pigmentosa (RP) cases." (PMID 40606666, 2025). "In retinitis pigmentosa, the implicated genes that appeared across multiple studies include MERTK, PDE6B, CERKL, and ABCA4." (PMID 36836473, 2023). "So far, more than 1000 mutations have been reported in ABCA4 across different cohorts leading to STGD1 and other retinal disorders like autosomal recessive cone-rod dystrophies, age macular degeneration and retinitis pigmentosa." (PMID 31934596, 2020). "The purpose of our study was to illustrate a data-driven deep learning approach to predict the causative genes of IRD in macular dystrophy caused by ABCA4 and RP1L1 in comparison with retinitis pigmentosa caused by EYS gene aberration and normal subjects." (PMID 31093368, 2019). "Moreover, multiple cases of various retinitis pigmentosa types were reported to be a result of alterations in other genes and uniparental isodisomy on chromosome 1: in the ABCA4 gene, in the USH2A gene, and in the CRB1 gene." (PMID 38002999, 2023). "Thus, we suspect that the phenotype of patient A1 with retinitis pigmentosa may be a result of variations in both ABCA4 and AHI1 genes, which highlights the genotypic variability associated with ABCA4-related retinitis pigmentosa." (PMID 33732702, 2021). "However, the broader context of ABCA4 mutations in Poland, especially in the case of retinitis pigmentosa patients, has never been tested." (PMID 31766579, 2019). "WGS detected previously overlooked SVs, including a partial exon 6 deletion in ABCA4 in patient P433 and a homozygous deletion affecting three genes, including NPHP1, in patient P440, who presented with retinitis pigmentosa and renal disease." (PMID 40926010, 2025). "The resulting dendrogram captures some of the known phenotypic similarities in IRDs such as Stargardt phenocopy genes (ABCA4, PRHP2 and PROM1), retinitis pigmentosa genes (RPGR and USH2A) and achromatopsia genes (CNGA3 and CNGB3)." (PMID 40567353, 2025). "Therefore, the term ABCA4 retinopathies (ABCA4R) has been introduced to describe a wide range of phenotypes, including STGD1, fundus flavimaculatus, bull’s eye maculopathy, CORD, and retinitis pigmentosa (RP)." (PMID 41234456, 2025).
retinitis pigmentosa (continued). "If the mouse model is the only source of information, it may be concluded that ALDH1A3 and RARβ play no role in anophthalmia and that ABCA4 plays no role in retinitis pigmentosa." (PMID 26343735, 2015).
age-related macular degeneration (48 papers, 2007 to 2025). Age-related loss of vision in the central portion of the retina (macula), secondary to retinal degeneration. "Zimura wasfirst tested in subjects with age-related macular degeneration but now alsofor cases with ABCA4-associated retinopathy." (PMID 32278709, 2020). "There have also been reports of ABCA4 dominant heterozygous mutations causing age-related macular degeneration (AMD, MIM #153800)." (PMID 31766579, 2019). "In case ad5 with AD macular degeneration caused by ABCA4, reports indicate that ABCA4 dominant heterozygous mutations may lead to age-related macular degeneration (AMD, MIM #153800)." (PMID 38785568, 2024). "ABCA4-associated retinopathies manifesting early in life progress more rapidly, while a later age of onset is associated with a milder prognosis and can be misdiagnosed as age-related macular degeneration (AMD)." (PMID 38755404, 2024). "Age-related macular degeneration (AMD) may be associated with ABCA4 variants and is characterized by the accumulation of visual cycle-byproduct lipofuscin." (PMID 37510153, 2023). "Variation in ABCA4 causes extensive clinical heterogeneity, from early-onset, severe disease, rapid-onset chorioretinopathy, to very late-onset mild phenotypes that can be misdiagnosed as age-related macular degeneration (AMD)." (PMID 35353811, 2022). "Diseases associated with ABCA4 include age-related macular degeneration and Stargardt disease." (PMID 33500538, 2021). "One study found that two out of eight patients with toxic maculopathy carried monoallelic mutations in ABCA4, a gene in which mutations have been associated with autosomal recessive Stargardt disease and the genetically complex age-related macular degeneration." (PMID 25884411, 2015). "The ABCA4 variants were also found in age-related macular degeneration (AMD)." (PMID 40062075, 2025). "However, it is important to note that variants in the ABCA4 gene can lead to a spectrum of phenotypical manifestations, one of which includes age-related macular degeneration (AMD)." (PMID 39000382, 2024). "From a disease perspective, Abca4−/−Rdh8−/− double knockout (dKO) mice are a photosensitive model of stress-induced photoreceptor degeneration, which is widely used for modeling age-related macular degeneration (AMD) pathology." (PMID 33563331, 2021). "The age of onset for patient ABCA4-47A carrying the p.Asn76Thr was 52 years according to the patient who was initially erroneously diagnosed with age-related macular degeneration in 2012." (PMID 29854428, 2018). "It has also been proposed that individuals carrying mutations in ABCA4 may have a higher risk of developing age-related macular degeneration (AMD)." (PMID 24763286, 2014). "Furthermore, the effect of lutein supplementation on macular pigment has been established in age-related macular degeneration, choroideremia, ABCA4-related disease and RP." (PMID 38066762, 2023). "Phenocopies of ABCA4-RD in this series included macular dystrophy, pattern dystrophy, cone dystrophy, advanced retinitis pigmentosa, Leber congenital amaurosis, drug toxicity, and age-related macular degeneration." (PMID 38066771, 2023). "Such patients may often be preferentially tested only for ABCA4 mutations, or be diagnosed with age-related macular degeneration and therefore receive no genetic diagnosis." (PMID 29555955, 2018). "For example, how much variation is there in expression of the three genes involved in age-related macular degeneration (ARMD)—complement factor H (Cfh), the retina-specific ATP-binding cassette transporter (Abca4), and apolipoprotein E (Apoe)?" (PMID 19727342, 2009). "Mutations in ABCA4 have been associated with autosomal recessive STGD (arSTGD), autosomal recessive retinitis pigmentosa (arRP), autosomal recessive cone-rod dystrophy (arCRD) and age-related macular degeneration (AMD)." (PMID 17277736, 2007).
age-related macular degeneration (continued). "In the Stargardt patient with no pathogenic ABCA4 mutations two variants in CFH were detected, one of which (rs1061170) had previously been reported to predispose to age related macular degeneration (AMD)." (PMID 22277662, 2012).
Macular dystrophy (42 papers, 2011 to 2025). Macular dystrophy is a nonspecific term for retinal degeneration, generally confined to the macula, usually presumed of genetic origin. "Even within the group of ABCA4-associated macular dystrophies there is a subgroup with predominantly perifoveal atrophy, in whom the preserved foveal center is associated with a maintained reading ability for many years." (PMID 39963372, 2025). "STGD is another ocular disorder that is focused on macular dystrophy but is caused by a mutation in the ABCA4 (ATP-binding cassette subfamily A member 4) gene, which encodes for the ATP-binding cassette (ABC) transporter protein." (PMID 39861752, 2025). "Heterozygous individuals in ABCA4 disease and control cohort harboring rare variants in macular dystrophy genes CDHR1, CHM, CRX, ELOVL4, PROM1, PRPH2, ROM1." (PMID 35353811, 2022). "Proband WGS research testing was available at the time of review and examination of Stargardt and macular dystrophy genes by WGS identified single exon heterozygous 1029bp deletion involving exon 18 of ABCA4, in addition to the pathogenic variant c.5461-10T>C." (PMID 35409265, 2022). "Significant sex imbalances have been observed in certain autosomally-inherited macular dystrophies (such as those associated with ABCA4, BEST1 and EFEMP1), although the underlying mechanisms remain unclear." (PMID 39632990, 2025). "Variants in the ABCA4 gene can be associated with autosomal recessive IRDs ranging from macular dystrophy (i. e., Stargardt disease) limited to the posterior pole to severe cone-rod dystrophy and rarely retinitis pigmentosa, both of the latter involving all of the retina." (PMID 39963372, 2025). "Although all our patients were diagnosed clinically with STGD, the overlapping of phenotypes between different macular dystrophies and several stages of ABCA4-associated retinopathy could result in a misdiagnosis of STGD with mutations in phenocopying genes, such as PRPH2, ROM1, CRX, or RPGR." (PMID 33841504, 2021). "In MST448-II:1, variants in both the ABCA4 and IMPG1 genes were considered potential contributors to the observed macular dystrophy." (PMID 40269797, 2025). "Accumulation of autofluorescent lipofuscin granules in the RPE is a symptom of ABCA4-mediated retinal and macular dystrophies." (PMID 37510362, 2023). "Heterozygous individuals in ABCA4 disease and control cohort harboring variants with MAF<0.005 and CADD score >25, in each macular dystrophy gene CDHR1, CHM, CRX, ELOVL4, PROM1, PRPH2, and ROM1." (PMID 35353811, 2022). "Panel-based NGS was performed to identify potentially disease-causing genetic variants in previously identified retinal or macular dystrophy genes, including the five known STGD genes (ABCA4, PROM1, PRPH2, VMD2, and ELOVL4)." (PMID 33988224, 2021). "For both “ABCA4 –Macular dystrophy—recessive” and “SCN1A –Seizures—dominant”, bins showing strong association correctly clustered with rare variants (GF < 0.00025)." (PMID 32271766, 2020). "For macular dystrophies, the most common gene by far was ABCA4 (autosomal recessive), whereas PRPH2 and BEST1 were implicated frequently in autosomal dominantly inherited macular dystrophies." (PMID 32423767, 2020). "In 1 individual, homozygosity for ABCA4 c.5882G>A; p.(Gly1961Glu) as well as ABCC6 (NM_001171.6) c.708_709dup9; p.(Trp237SerfsTer22) variants resulted in a macular dystrophy phenotype as well as pseudoxanthoma elasticum, with both ocular and dermatological features noted." (PMID 38219857, 2024). "Moreover, there are other IRD disease genes where a significant proportion of pathogenic alleles lie within intronic or non-coding regions such as ABCA4 and the PRDM13 associated North Carolina Macular Dystrophy locus." (PMID 35409265, 2022). "The ABCA4 gene was studied because it is the most frequent gene responsible for macular dystrophy in the young and the retinal phenotype stated in the available reports were suggestive of macular dystrophy." (PMID 28061825, 2017).